CD4 (CD4 molecule)
Diseases named in the same sentence as CD4 in open-access papers (continued):
Sharing a sentence is not in itself a finding about the gene and the disease.
cutaneous melanoma (27 papers, 2017 to 2025). A primary melanoma arising from atypical melanocytes in the skin. "In addition, studies have found that CENPF is positively associated with CD4+ memory T-cell phenotypic markers and negatively correlated with memory T-cell survival regulators in cutaneous melanoma." (PMID 36644760, 2022). "The survival rate seems to be higher for those with Hodgkin’s, cutaneous melanoma, CD4 nadir ≥100 cells/μL, and CD4:CD8 ratio ≥0.4." (PMID 41304899, 2025). "In cutaneous melanoma, CENP‐F is associated with CD4+ T cell markers; high CENP‐F expression is negatively correlated with CD4+ T cell survival regulators, leading to premature CD4+ T cell depletion and immunosuppression." (PMID 40387105, 2025). "In light of recent research emphasising the critical role of MHC II‐dependent CD4+ T‐cell immunity in combating cutaneous melanoma, we deeper analysed the interplay between RECQL4 and MHC‐II‐associated molecules." (PMID 39812592, 2025). "ERBB 1 (EGFR) induces the infiltrating levels of B cells, CD4+ T cells, Neutrophils, and Dendritic Cells in cutaneous melanoma." (PMID 33732282, 2021). "A recent report using multi-parameter flow cytometric profiling revealed that proportions of naive CD45RA+CD4+ T cells in mLN of stage III cutaneous melanoma patients, inversely correlated with the frequencies of CD8+ T cells." (PMID 33013886, 2020). "In skin cutaneous melanoma (SKCM), the PDPN expression was negatively correlated with infiltration levels of various immune cells, including CD4 + T cells, CD8 + T cells, M1 macrophage, and NK cells, and positive correlated with M2 macrophage and Treg cells." (PMID 38167452, 2024). "We found expression of AICDA in both normal skin and cutaneous melanoma and a positive correlation of AICDA with B cell, plasma cells as well as CD4+ and CD8 + T cells signatures." (PMID 37291228, 2023). "Skin cutaneous melanoma (SKCM) had significantly similar cell populations of MSCs (p = 0.3872), NK cells (p = 0.05057), and CD4+ cells (p = 0.5715) to BCC." (PMID 36612301, 2023). "Our results showed that M2 macrophages, resting CD4+ memory T cells, resting mast cells, follicular helper T cells, M1 macrophages and CD8+T cells were abundant in cutaneous melanoma in situ." (PMID 34737950, 2021). "Compared to one study of cutaneous melanoma metastasis, the density of CD3 and CD68CD163 was similar, with a higher density of CD4 and Foxp3, and lower density of CD8 cells." (PMID 28903377, 2017). "In another study, CD4+ T cells from SLN of 13 cutaneous melanoma patients (positive and negative LN were included) displayed a TH2 skewed gene signature in association with increased production of VEGFA." (PMID 33013886, 2020). "Major histocompatibility complex class II (MHC II) molecules, which are highly expressed in cutaneous melanomas, represent the canonical ligands of LAG-3, as they do for CD4, however, the proline-rich D1 domain allows LAG-3 to bind with higher affinity to MHC II than to CD4." (PMID 37004702, 2023). "Also, we found that ERBB1/2/3 and immune infiltration cells (B cells, CD4+ T cells of CD8+ T cells, macrophages, neutrophils, and dendritic cells) influenced the 5 years survival of patients with cutaneous melanoma, while ERBB4 may not affect the 5-year survival of cutaneous melanoma patients." (PMID 33732282, 2021).
nasal polyps (27 papers, 2009 to 2025). "Significantly increased infiltration of pmTOR+ inflammatory cells and decreased infiltration of Foxp3+CD4+ Tregs into nasal polyps was observed, with an inverse association." (PMID 19250527, 2009). "Our study suggests that Prevotellaceae protect against nasal polyps, potentially by reducing their risk through inhibiting CD39 levels on CD39+ activated CD4 regulatory T cells and CD45RA on naive CD4+ T cells." (PMID 39346904, 2024). "IL‐10+ GZMK+ CD4+ T cells have primarily been described in tumours, as well as nasal polyps from chronic rhinosinusitis patients." (PMID 38707998, 2024). "The recruitment of CD4+ T cells into the nasal mucosa is under the influence of regulatory T (Treg) cells, which are thought to play a pivotal role in the formation of nasal polyps by modulating the equilibrium between Th1 and Th2 immunity." (PMID 38680486, 2024). "Prevotellaceae increased the risk of nasal polyps by decreasing CD39 on CD39+ activated CD4 regulatory T cells and CD45RA on naive CD4+ T cells, which are protective factors against nasal polyps." (PMID 39346904, 2024). "More specifically, there was an observed increase in activated Treg cells within the CD4+ T cell population in nasal polyps compared to Peripheral Blood Mononuclear Cells." (PMID 38680486, 2024). "Chronic sinusitis frequently coexists with nasal polyps, characterized by eosinophil recruitment due to abnormal activation of immune cells, such as CD4+ T cells and Th2 cells." (PMID 39346904, 2024). "During the recruitment of CD4+ T cells into the nasal mucosa, regulatory T (Treg) cells are considered to play a key role in the formation of nasal polyps by modulating the balance of Th1 and Th2 immunity." (PMID 35378904, 2022). "Analyses of nasal polyps that develop due to chronic upper airway inflammation indicated that ~20–40% of CD4+ T cells produce IL-21, as observed by both flow cytometry and immunohistochemistry." (PMID 30190721, 2018). "Given the abundant expression of IL-17 by CD4+ T cells derived from the healthy nasal mucosa in addition to nasal polyps, these cells were characterized further." (PMID 26684290, 2016). "Clonality was examined by T-cell receptor variable β-chain (TCR Vβ) analysis with the immunoSEQ assay and compared in IL-17RB+CD4+ and IL-17RB−CD4+ cells sorted from nasal polyp explant cultures of 4 patients with CRSwNP." (PMID 26684290, 2016). "IL-12 enhances IL-21 and IFN-γ production in CD4+ T cells in nasal polyps, especially the percentages of Tfh-like cells." (PMID 26239551, 2015). "Only in CRSwNP, a significantfraction of T cellsproduced the Th2 cytokinesIL-4 and IL-5, while nasal polyps from CF patients were characterized by a higher CD4/CD8 T cell ratio and an increased number of Th17 cells." (PMID 24911279, 2014). "Our results indicate that the number of Foxp3+CD4+ Tregs negatively correlated with the number of pmTOR+ inflammatory cells in nasal polyps (b = -0.74, P < 0.01)." (PMID 19250527, 2009). "After treatment with rapamycin, a significant increase in the frequencies of CD4+CD25+ cells and Foxp3+CD4+ Tregs in nasal polyps was found compared to untreated nasal polyps (P < 0.05 by the paired t-test)." (PMID 19250527, 2009). "In order to more precisely identify Foxp3+ Tregs in nasal polyps, we simultaneously evaluated CD4 and Foxp3 by double immunofluorescence staining." (PMID 19250527, 2009). "For intragroup comparison, we found the percentages of CD4+CD25+ and Foxp3+CD4+ cells to be significantly decreased in nasal polyps compared to the control (P < 0.05 by the unpaired t-test)." (PMID 19250527, 2009). "The number of Foxp3+CD4+ cells decreased significantly in nasal polyps compared to control nasal tissues (P < 0.05 by the unpaired t-test)." (PMID 19250527, 2009). "Our study suggests that Methanobrevibacter may contribute to an increased risk of nasal polyps by affecting the levels of CCR2 on CD62L+ myeloid dendritic cells and CD3 on CD4 regulatory T cells." (PMID 39346904, 2024).
nasal polyps (continued). "Furthermore, Individuals experiencing nasal polyposis exhibit a diminished presence of CD4+ T cells and an augmented prevalence of CD8+ T cells." (PMID 38680486, 2024). "Additionally, the percentage of PD-1+ cells among both CD8+ and CD4+ T cells in the paranasal sinus mucosa was significantly higher than that in nasal polyps." (PMID 38426098, 2024). "Furthermore, ectopic lymphoid structures consisting of memory CD4+ T cells were found in nasal polyps of eosinophilic chronic rhinosinusitis patients, indicating that the persistence of inflammation is controlled by these structures." (PMID 29951134, 2018). "Indeed, in nasal polyps, biased differentiation of CD4+ T-cells into Th17 and Treg cells resulted in an imbalance in Th17 and Treg cells, which lead to distinct inflammatory patterns (eosinophilic vs neutrophilic inflammation) in nasal polyps." (PMID 26962811, 2016). "Although CD4+ T cells are recognized to play an important role in the inflammatory response of nasal polyps (NPs), the biological functions of CD8+ T cells in polypogenesis remain unclear." (PMID 27468819, 2016). "In order to evaluate whether Foxp3+CD4+ cells were associated with pmTOR+ inflammatory cells, we investigated the quantitative relationship between the numbers of pmTOR+ inflammatory cells and Foxp3+ CD4+ Tregs in nasal polyps by linear regression." (PMID 19250527, 2009). "Given that Foxp3 is also expressed by other non-CD4+ T cells, we evaluated the change in the Foxp3+ Treg population in nasal polyps by flow cytometric analysis to further support our hypothesis." (PMID 19250527, 2009). "Additionally, the remarkable recovery of CD4+CD25+ cells conveyed their plasticity hence subverted Tregs in nasal polyps could once more regain their suppressive role after treatment." (PMID 33238997, 2020). "A tendency was also observed for the percentage of PD-1+ cells among CD4+ and CD8+ T cells to be higher in the nasal polyps of patients with CRS patients than in the healthy controls." (PMID 38426098, 2024). "Methanobrevibacter inhibited CCR2 on CD62L+ myeloid dendritic cells, a protective factor against nasal polyps, or mediated elevated levels of CD3 on CD4 regulatory T cells, which ultimately led to an increased risk of polyps." (PMID 39346904, 2024). "We then analyzed metallothionein, RCAS1, CD25, CD4, and CD68 in a sampling of 50 nasal polyps using the immunohistochemistry method." (PMID 20214821, 2010). "In order to evaluate the frequency of Foxp3+ Tregs in nasal polyps after rapamycin treatment, we examined CD4, CD25, and Foxp3 biomarkers in isolated cells from nasal polyps by flow cytometric analysis." (PMID 19250527, 2009). "The role of Tregs in CRS remains complex, with studies reporting that CD25+/CD4+ FOXP3+ T cells are significantly higher in CRS with nasal polyps than in CRS without nasal polyps." (PMID 38812518, 2024). "The proportion of CXCR5+TIM-3-PD-1+ cells among both CD8+ and CD4+ T cells was significantly elevated in the paranasal sinus mucosa (CD8+: p=0.0027; CD4+: p=0.024); and in the nasal polyps (CD8+: p=0.042; CD4+: p=0.039); of patients with CRS than the proportion in healthy controls." (PMID 38426098, 2024). "In addition, a low frequency of CD4+ T cells and a high frequency of CD8+ T cells were observed in patients with nasal polyposis." (PMID 35378904, 2022). "Moreover, the results for CD4, CD25, and Foxp3 biomarkers in isolated T cells by flow cytometry showed that the frequencies of CD4+CD25+ cells and Foxp3+CD4+ Tregs significantly increased in nasal polyps after rapamycin stimulation." (PMID 19250527, 2009). "The aim of the present study was to detect and characterize C. albicans-specific CD4+ and CD8+ T cells in patients with CRS, with and without nasal polyps." (PMID 34063898, 2021). "No other examined antigens (such as CD25, CD4, or CD68) were identified in the neutrophilic nasal polyps." (PMID 20214821, 2010).
pulmonary sarcoidosis (27 papers, 2005 to 2026). Sarcoidosis affecting the lung parenchyma. "At diagnosis, one of the main features of pulmonary sarcoidosis is an increased lymphocyte T CD4 count and the CD4/CD8 ratio in the BALF." (PMID 40217830, 2025). "A considerable proportion of individuals with pulmonary sarcoidosis exhibit a reduction in peripheral blood lymphocyte count, whereas approximately half experience a decrease in peripheral blood CD4+ T cells and CD8+ T cells." (PMID 40755006, 2025). "Specifically, 86 (62.32%) pulmonary sarcoidosis patients and 51 (42.86%) intrathoracic lymph node TB patients had reduced CD4+ T lymphocytes (p = 0.47)." (PMID 40755006, 2025). "More recently, one study has used the proportions of circulating PD-1+ CD4+ memory T cells and PD-1+ regulatory T cells to predict treatment response to prednisone in pulmonary sarcoidosis." (PMID 39629229, 2024). "In pulmonary sarcoidosis, bronchial lavage is characterized by an increased lymphocyte count with a high CD4/CD8 ratio." (PMID 38322384, 2021). "Here, we characterize systemic and local CD4+ T cell immune function in pulmonary sarcoidosis subjects clinically experiencing disease progression or spontaneous resolution." (PMID 29234685, 2017). "This article reviews the immunological etiology and mechanisms of pulmonary sarcoidosis, systematically discussing its pathogenetic basis, core immune mechanisms, and the role of key immunological biomarkers (such as sIL-2R, CD4+/CD8+ ratio in BALF, and HRCT) in diagnosis and assessment." (PMID 41767532, 2026). "Increased proportions of circulating PD-1+CD4+ memory T cells and PD-1+ regulatory T cells and decreased proportions of CD25+CD4+ memory T cells associate with good FVC response to prednisone in pulmonary sarcoidosis, representing promising new blood biomarkers for prednisone efficacy." (PMID 38715030, 2024). "To examine this immunologic relationship between CD4+ T cells and clinical course, we focused on longitudinal changes in CD4+ T cell subsets and their relationship to disease phenotype in patients recently diagnosed with pulmonary sarcoidosis." (PMID 36893197, 2023). "Next, we evaluated whether a similar population of CD4+ T cells could also be identified in pulmonary sarcoidosis." (PMID 35668129, 2022). "Pulmonary sarcoidosis was also associated with a low CD4 count: 8 (62%) patients versus 17 (13.0%) of the patients without pulmonary sarcoidosis (Fisher’s exact test p < 0.001)." (PMID 29371544, 2017). "In the present study, we performed intercellular cytoplasmic cytokine staining (ICCS) of CD4+ helper T cells and aimed to examine the different subsets of these cells during the courses of relapsing and remitting pulmonary sarcoidosis in patients after corticosteroid withdrawal." (PMID 26845566, 2016). "In conclusion, these data demonstrate that there are increased numbers of CD4+ IFN-γ producing T cells in induced sputum from patients with pulmonary sarcoidosis, in accordance with the shift towards the Th1 response known to exist in BALF and peripheral blood." (PMID 15978129, 2005). "An IL‐2 receptor level greater than 150 pg/mL is associated with a sensitivity of 61% and a specificity of 93% for the diagnosis of NS; (ii) assay of the CSF CD4/CD8 ratio, with parallel use of this assay in pulmonary sarcoidosis diagnosis." (PMID 39279263, 2024). "An increased number of CD3+CD4+ T lymphocyte cells was observed in bronchoalveolar lavage fluid (BALF) and other affected tissues of pulmonary sarcoidosis patients, resulting in an increased CD4/CD8 ratio, considerably higher than 3.5." (PMID 35615369, 2022). "In pulmonary sarcoidosis, we noticed a decrease in TREM-1+CD14+ cells, CD4+ T cells, DLCO and increase in CD8+ T cells in relationship with HRCT images acquired from the most benign to the most severe type." (PMID 32508528, 2020). "The bronchoalveolar lavage CD4+/CD8+lymphocytes ratio in PBC patients without lung involvement was similar to that in pulmonary sarcoidosis." (PMID 36836775, 2023).
pulmonary sarcoidosis (continued). "Pulmonary sarcoidosis is an inflammatory disease, characterized by an accumulation of CD4+ lymphocytes and the formation of non-caseating epithelioid cell granulomas in the lungs." (PMID 21059230, 2010). "In one study of pulmonary sarcoidosis patients undergoing bronchoalveolar lavage (BAL), there was a was a significant relationship between an increase in the number of CD4 positive T cells in the BAL fluid and a decrease in the absolute number of CD4 positive T cells in the peripheral blood." (PMID 20140091, 2010). "In 2006, Nobata K reported the first case with typical pulmonary sarcoidosis, characterized by an increase in BAL lymphocyte percentages and CD4/CD8 ratio, biopsy evidence of non-caseating epithelioid cell granulomas and high concentrations of sarcoid-related biomarkers." (PMID 35407673, 2022).
renal failure (27 papers, 2011 to 2025). "Having a CD4 count of <50 cells/uL increased the risk of renal insufficiency by 2.35 times compared to having a CD4 count >200 cells/uL (95%CI 1.33–4.16)." (PMID 21407815, 2011). "p = 0.025), suggesting a diminished regenerative or stem-like capacity in the CD4+ T cell subset of patients with renal insufficiency." (PMID 40584830, 2025). "CD4+ T cells from the renal insufficiency (PTRI) group displayed a significantly lower mRNAsi compared to those from the control (Ctrl) group (p < 0.05)." (PMID 40584830, 2025). "To further examine lineage commitment within CD4+ T-cell subsets, we constructed pseudotime trajectories that included CD4+ T cells, Th17 cells, and Treg cells for both control (Ctrl) and renal insufficiency (PTRI) groups." (PMID 40584830, 2025). "Research has indicated that patients with severe renal insufficiency have compromised cellular immune function, with a decreased CD4/CD8 ratio, an elevated Th1/Th2 ratio, and exhaustion of CD4 + and CD8 + T cells." (PMID 41291834, 2025). "Accumulation of uremic toxins in kidney failure alongside increased oxidative stress leads to a build-up of pro-inflammatory cytokines such as CD4+ and CD28 as well as CD14+ and CD16++ monocyte populations." (PMID 36979905, 2023). "Additionally, they found a correlation between CD38+ HLA-DR+CD4+ T cells and ferritin, renal insufficiency, acute kidney disease, and APACHE III score, indicating a relationship between disease severity and activation of CD4+ T cells." (PMID 36675642, 2023). "Moreover, patients with kidney failure have the lowest CD4+ T cell counts and positive correlations were established between eGFR and CD4+ T cell counts in HIV-1–infected patients." (PMID 35316209, 2022). "Therefore, renal insufficiency could be the underlining cause of proteinuria arising from an advanced stage HIV infection and a declined CD4 count." (PMID 29606987, 2018). "It is established that elderly patients and those with kidney failure have higher numbers of CD28 and CD4 null cells and advanced differentiated cells, which may result in the increased likelihood of cytokine storm and acute lung injury." (PMID 36979905, 2023). "The general distribution of CD4 and CD8 CD45RC subsets in these patients was similar to that observed in the 608 healthy controls, indicating that kidney failure and dialysis had no impact on CD45RC expression by T cells." (PMID 23894540, 2013).
end-stage renal disease (26 papers, 2012 to 2025). "The activation of cell cycle-related modules may be attributed to impaired proliferation of activated CD4+ T cell subsets, as observed in patients with end-stage renal failure." (PMID 40370459, 2025). "The number of CD4+IFN-γ−IL-17+ Th17, CD4+IFN-γ+IL-17− Th1 and CD4+IFN-γ+IL-17+ Th1/17 cells were significantly increased in patients with End-Stage Renal Failure (ESRF) compared to the HC." (PMID 26400627, 2015).